CASP8 (caspase 8)
Diseases named in the same sentence as CASP8 in open-access papers (continued):
Sharing a sentence is not in itself a finding about the gene and the disease.
tumor (continued). "Caspase-8 plays a pivotal role in an array of cellular signaling pathways and is essential for the governance of programmed cell death mechanisms, inflammatory responses, and the dynamics of the tumor microenvironment." (PMID 39726605, 2024). "Furthermore, Caspase-8 can lead to a decrease in Kupffer cells (hepatic macrophages, KCs) after partial hepatectomy for HCC, which will facilitate tumor cell proliferation and increase the risk of HCC recurrence." (PMID 39726605, 2024). "Theoretically, GSDMC can sensitize tumor cells to the treatment of any drugs that could activate caspase-6 or caspase-8, or could stimulate antitumor immunity response." (PMID 37883181, 2024). "Deletion of GSDMC or caspase-8 significantly decreased sensitivity of tumor cells to PARPi." (PMID 37883181, 2024). "However, birinapant proved effective in retarding tumor growth only when combined with Casp8 knockdown, accompanied by a significant survival benefit." (PMID 39458950, 2024). "As a simple example, caspase-8 has been reported to have both pro- and anti-tumor effects." (PMID 38553639, 2024). "Indeed, caspase-8 has an antitumorigenic effect on the primary tumor cells and the TME by regulating the activation of B and T lymphocytes, as well as the differentiation and polarization of macrophages." (PMID 39625520, 2024). "In summary, our findings indicate that PRF treatment may potentially exert a tumor-suppressive effect by upregulating caspase 8 and caspase 9 gene expression, leading to the activation of both intrinsic and extrinsic apoptosis pathways." (PMID 39684700, 2024). "Nevertheless, it is important to investigate whether caspase-8 regulates the inflammatory TME to promote or suppress tumor growth." (PMID 39625520, 2024). "It is clear that PRKCSH is critical for regulating the balance between the two caspase-8 modes of action, which may be involved in the regulation of NK cell-mediated antitumor immunity as well as tumor cell growth." (PMID 38200153, 2024). "Additionally, berberine was found to trigger apoptosis by activating the intrinsic pathway, as it activates caspase-3 and caspase-8, which in turn release cytochrome C, in addition to promoting ROS production in tumor cells." (PMID 38334679, 2024). "In addition, high expression of caspase-8 can prevent typical endogenous apoptosis and induce mitosis, thereby promoting tumor progression." (PMID 38877579, 2024). "In addition to targeting tumor cells, Trabectedin induces apoptosis of macrophages in the tumor by activating caspase 8 through a TNF-related ligand-dependent mechanism." (PMID 39003350, 2024). "To examine the effect of Casp8 deletion on tumor formation we treated WT and Casp8−/− mice with the synthetic carcinogen 4-nitroquinoline-1-oxide (4NQO), which captures the heterogeneity and many of the hallmarks of human OSCC, mimicking the carcinogenic effects of tobacco and alcohol ingestion." (PMID 39625985, 2024). "Therefore, caspase-8 is an important target for improving the tumor microenvironment and enhancing antitumor immunity." (PMID 38200153, 2024). "Tumor mutations in CREBBP/EP300 and CASP8 were significantly associated with Th2 infiltration." (PMID 38672668, 2024).
tumor (continued). "In vivo studies using female athymic BALB/c nude mice supported these findings, with intraperitoneal α-mangostin administration leading to significant suppression of tumor volume and weight, accompanied by upregulation of cleaved caspase-3 and caspase-8 expression in tumor tissues." (PMID 39595559, 2024). "Notably, the mutation frequencies of key ICDRGs, such as PI3KA, NLRP3, CASP8, and TLR4, highlight the potential role of genetic alterations in modulating immune responses within the tumor microenvironment." (PMID 39372411, 2024). "Detection of activated caspase 8 in the tumor cells also confirmed the results." (PMID 36661524, 2023). "To explore the underlying mechanism of the Casp8-mediated antitumor immune response, we compared RNA sequencing data to identify the differentially regulated signaling pathways between Casp8-8 knockout and control tumors in a B16F10 tumor-bearing mouse model." (PMID 36635765, 2023). "In the tumor microenvironment, CASP8 showed correlations with various immune cell types." (PMID 38186679, 2023). "After absorption of PC in tumors and irradiation with laser, ROS are produced in tumor cells to induce extracellular apoptosis by increasing the activity of Caspase-8 and Caspase-3 and decreasing the activity of Bcl-2, an important factor for cell proliferation." (PMID 37994159, 2023). "GSDME, caspase 3, and caspase 8 are more abundantly expressed in tumor tissue." (PMID 37752941, 2023). "Tumor-associated macrophages are involved in pyroptosis through the classical pathway induced by the caspase-1 cleavage of GSDMD and the pathway mediated by the caspase-8 cleavage of GSDME and the granzyme action of GSDMB." (PMID 37542283, 2023). "CASP4, CASP6, CASP8, IL18, and PYCARD were associated with clinical stage, which means that IL18 and PYCARD may be involved in tumor progression." (PMID 36882663, 2023). "In addition, caspase-8 in tumor cells can be activated by TNF-α to cleave GSDMC, while in murine macrophage, activation of caspase-8 in the context of TAK1 inhibition results in cleavage of both GSDMD and GSDME." (PMID 36823153, 2023). "Similarly, CASP8-induced immune escape through apoptotic inhibition is another mechanism evolved by HPV− CNAlow HNSCs to survive a high anti-tumour infiltration." (PMID 37277866, 2023). "Indeed, Caspase-8 plays an antitumorigenic role in the primary tumor cells and in the tumor microenvironment (TME) by regulating B and T lymphocyte activation and macrophage differentiation and polarization." (PMID 37444381, 2023). "However, the role of Casp8 in tuning the tumor immune microenvironment remains controversial due to the complicated crosstalk between immune-tolerogenic apoptotic cell death and immunogenic cell death cascades." (PMID 36635765, 2023). "Therefore, in our research, we comprehensively evaluated the importance of ATGs in OV and identified the prognostic signature (namely FOXO1 and CASP8), which was related to tumor immune microenvironment and sensitivity to immunotherapy/ chemotherapy." (PMID 37120633, 2023). "Chemo‐drugs may activate caspase 3, triggering pyroptosis via the cleavage of GSDME16 Tumor necrosis factor‐alpha (TNF‐α) activates caspase 8 in tumor cells to activate pyroptosis." (PMID 37752941, 2023). "TCS significantly promoted the activation of Caspase 9, Caspase 8 and Caspase 3 in tumor tissues." (PMID 36674931, 2023).
tumor (continued). "Since Caspase 8 (CASP8) is frequently mutated in OSCCs, we were interested to explore a potential interaction between tumour‐infiltrating lymphocytes (TILs) and CASP8 activation using high‐content image analysis of human tumour (n = 32) sections." (PMID 37443405, 2023). "In addition, in cancer cells, the binding of c-FLIP to FasL+ EV interferes with the activation of caspase-8, thereby promoting tumour invasiveness and metastasis formation." (PMID 36011012, 2022). "Caspase-8 expression is retained in many tumors suggesting that its apoptotic activity may switch off and its function rewired to sustain tumor growth." (PMID 35853963, 2022). "Thus, to find out the balance point of CASP8 in anticancer function and tumor-promoting action is of clinical significance." (PMID 35242200, 2022). "Moreover, NLRP3 mediates pyroptosis by triggering caspase 8 activation, indicating its roles in regulating tumor cell death and tumor–immune interaction." (PMID 36497253, 2022). "Finally, caspase-8 activation in glutamine-deprived tumor cells was significantly inhibited in the presence of the GCN2 inhibitor, A92." (PMID 36302756, 2022). "Our finding showed that CASP8 was downregulated in tumor tissues and suggested its negative association with the occurrence of LUAD." (PMID 35866781, 2022). "Granzyme B (GzmB) and Granzyme A (GzmA) are apoptotic proteinase-like serine proteases that can activate caspase-3 and caspase-8 and be transferred to target cells by cytotoxic lymphocytes to trigger cell apoptosis, pyroptosis, and kill virus-infected cells and tumor cells." (PMID 36605130, 2022). "We show that glutamine starvation triggers a FADD and caspase-8-dependent and mitochondria-operated apoptotic program in tumor cells that involves the pro-apoptotic TNF-related apoptosis-inducing ligand receptor 2 (TRAIL-R2), but is independent of its cognate ligand TRAIL." (PMID 36302756, 2022). "Moreover, in vivo animal experiments further confirm that PEG/ZIF-8@HF shows anti-tumor effect by up-regulating the pro-apoptotic proteins caspase-3 and caspase-8, and down-regulating the migration-promoting invasion protein MMP-9." (PMID 35373691, 2022). "In the presence of tumor necrosis factor-alpha (TNF-α), caspase-8 is activated in tumor cells." (PMID 35883480, 2022). "STE029 could sensitize Gefitinib by inhibiting EGFR/PI3K/Akt pathway, blocking the tumor cell cycle and proliferation and inducing apoptosis through caspase-8 and caspase-9 dependent pathway." (PMID 36419390, 2022). "Together with the observation that silencing TRAIL-R2, FADD or Caspase-8 expression inhibits apoptosis induced upon glutamine limitation, all these findings point to a crucial role of the extrinsic pathway of apoptosis in tumor cell death under conditions of amino acids shortage." (PMID 36302756, 2022). "This study not only illustrates a pyroptotic pathway linked with metabolites but also identifies an unreported principal axis extending from ROS-initiated DR6 endocytosis to caspase-8-mediated cleavage of GSDMC for potential clinical application in tumor therapy." (PMID 34012073, 2021). "The impact of both WT and MT caspase-8 proteins on cytokine levels suggested that the expression of these proteins in tumor cells may alter the tumor microenvironment in vivo." (PMID 34362880, 2021). "Dysregulated caspase-8 expression causes an imbalance between the apoptotic and non-apoptotic functions not only in the primary tumor but also in the TME." (PMID 33026575, 2021).
tumor (continued). "Taken together, carboplatin, paclitaxel, and birinapant combination treatments are synergistic and result in additional Caspase 8-independent tumor cell death and could benefit patient subpopulations who are resistant to apoptotic treatments." (PMID 34088893, 2021). "As contributors to PCa heterogeneity, tumor cells that are strongly dependent on NF-κB signaling and cytokine production, but not on the AR pathway, may have a selective advantage in retaining caspase-8 expression." (PMID 34482382, 2021). "All these results showed that Casp8 played a critical role in tumor progression." (PMID 33934451, 2021). "In the regulation of tumor cell survival, caspase-8 also plays a controversial role." (PMID 34482382, 2021). "Whether caspase-8 regulates the inflammatory tumor milieu in favor of tumor promotion or suppression, should be further investigated, in order to evaluate the clinical relevance of caspase-8 as a modulator of the TME." (PMID 33026575, 2021). "The present study revealed both RIPK1/RIPK3/MLKL and RIPK1/caspase-8/caspase-3 pathways were inhibited in TNBC tumor samples and AQP1-expressing cell lines, which is in agreement with our presumption that both RIPK1-dependent necroptosis and apoptosis are attenuated by AQP1." (PMID 33980862, 2021). "Iressa combined with NuF induced the tumor caspase-8 cleavage product." (PMID 34064322, 2021). "Genetic loss of TNF and its death-signaling molecules (e.g., Tnfr1 and Casp8) led to uncontrolled tumor growth, whereas loss of molecules involved in ubiquitinating RIPK1 (e.g., Traf2 and Birc2/3) resulted in tumor rejection following immune checkpoint blockade." (PMID 34752416, 2021). "Whether caspase-8 regulates the inflammatory tumor milieu in favor of tumor promotion or suppression, and should be further investigated." (PMID 33026575, 2021). "In fact, in many tumors, caspase-8 expression is retained or even increased, raising the question whether caspase-8 promotes tumor development and progression under certain circumstances." (PMID 34482382, 2021). "In animal models, the combined treatment of ZD55-SATB1+DTX and endocrine therapy effectively inhibited the growth of xenograft tumor, accompanied by increased expression of caspase-3 and caspase-8, and decrease expression of Bcl-2 and angiogenesis marker CD31 compared to other treatment groups." (PMID 33613773, 2021). "To determine whether caspase-3 and caspase-8 are activated in tumor, we examined for the presence of pro-form and its cleavage products using western blots." (PMID 34064322, 2021). "Downregulation of the death suppressor Bcl-2 and activation of caspase-8 and bax might be inhibiting tumour growth and progression through promoting apoptosis." (PMID 34181325, 2021). "Moreover, the expression of MKI67 increased with higher levels of tumor PD-L1 in C01, C11, and C12, while the expression of certain apoptotic genes, such as CASP8 in C01 and C12, and CASP3 in C11, was downregulated." (PMID 33754038, 2021). "Epigenetic regulation of CASP8 signifies the role of pro-apoptotic molecules in tumor progression." (PMID 34771655, 2021). "Interestingly, 81.8% (9/11) nuclear positive were detected in high caspase-8 group in PCa samples, which was consist with the recent study of the correlation between the nuclear caspase-8 and tumor treatment resistance." (PMID 34482382, 2021). "Therefore, we assessed the effects of inducible expression of WT and MT caspase-8 on tumor immune profiles using an immunocompetent mouse model of HNSCC." (PMID 34362880, 2021). "Furthermore, LPEPS oral administration induced tumor apoptosis by activating caspase cascade, including caspase-8, caspase-9, and caspase-3." (PMID 34945611, 2021).
tumor (continued). "This would provide us more valuable information about modified factors by Caspase-8, which could be used as new drug targets to reduce the tumor-supportive properties of the TME and to improve the tumor response to the classical therapies." (PMID 33026575, 2021). "Such possibility seems to be supported by the results of our study of the colon samples of patients with CRC in which we observed an increased number of neurons with caspase 8 immunoreactivity (CASP8-Ir) within the myenteric ganglia in the vicinity of tumour tissue." (PMID 32403316, 2020). "However, single-agent birinapant proved effective in delaying tumor growth only when combined with Casp8 knockdown, a phenomenon that was accompanied by a significant survival benefit." (PMID 33108350, 2020). "It has been hypothesized that the death receptor signalling pathway DR5/FADD/caspase-8 could promote the development of metastases mediated by tumour cells with acquired mechanisms of apoptosis resistance." (PMID 32847023, 2020). "Likewise, our results here explain the reason why PCBP1 downregulation or depletion would be an important strategy to tumor cell survival by downregulations of p62 and caspase-8." (PMID 32922440, 2020). "Expression of casp-8 can be enhanced via chemical compounds such as indolones, MX-2060 (by Maxim pharmaceutical company, Kenya) and dichlorobenzyl carbamates to induce apoptosis in tumor cell." (PMID 35047986, 2020). "Mechanistically, MDSCs of Tnfr-deficient mice displayed increased caspase-8 cleavage which induces apoptosis, and lower levels of c-FLIP, a natural caspase-8 inhibitor, which causes reduced accumulation of MDSCs in the TME along with a reduced tumor-suppressive capacity." (PMID 32733461, 2020). "Downregulation of the death suppressor bcl-2 and activation of caspase-8 and bax could inhibit tumor growth through promoting apoptosis." (PMID 31118873, 2019). "Furthermore, western blotting and an immunohistochemistry assay showed that the levels of Caspase-3, Caspase-8 and Bax in the tumor tissues were significantly increased, while the level of Bcl-2 decreased in a dose-dependent manner." (PMID 30651572, 2019). "Moreover, Western blot was used to examined the key cell apoptosis regulators and found that miR‐139‐5p/miR‐940/miR‐193a‐5p mimic enhanced the protein expression of the active forms of caspase 3, caspase 7 and caspase 8 in the tumour tissues." (PMID 30710422, 2019). "Furthermore, by transducing B16 tumor cells with caspase-8 protein, another member of the cysteine protease family which is implicated in apoptosis, cell death with apoptotic features was induced." (PMID 31480289, 2019). "Necroptosis induction in caspase-8 low tumor types, however, has been poorly investigated so far." (PMID 31192209, 2019). "Results showed 49.38% of the tumour tissues had increased p62 expression compared with the median value and Spearman correlation analysis confirmed that p62 expression was positively correlated with Caspase 8 (pho = 0.499, P < 0.01)." (PMID 30941888, 2019). "For example, evidence exists that indicates a possible tumor suppressor function of Casp8." (PMID 30598363, 2019). "However, intron retention has emerged as a widespread mechanism for the inactivation of tumor suppression regulators (e.g., CASP8)." (PMID 30795533, 2019). "In vivo, CASP8-mutant xenografts have been found to have significantly higher engraftment rates and tumor burden, and lower survival compared to wild-type xenografts, suggesting that tumors carrying these mutations may be more aggressive." (PMID 31844556, 2019). "Considering that -652 InsDel and Asp302His could have an influence on tumor surveillance and the anti-tumor response of T-lymphocytes, we for the first time correlated caspase 8 genotypes with the concentration of TILs." (PMID 31467295, 2019).